UTRN (utrophin)
Description:
May play a role in anchoring the cytoskeleton to the plasma membrane.
Synonyms: DMDL; DRP1; DRP
Tractability: Small molecule: a drug acting on it is in phase 2 or 3 trials; a structure with a bound ligand is known; a high-quality ligand is known. Antibody: its Gene Ontology location is reachable by antibodies, with high confidence; UniProt places it where antibodies can reach, with medium confidence; the Human Protein Atlas places it where antibodies can reach. PROTAC: ubiquitination databases record sites on it; its protein half-life has been measured; a small molecule that binds it is known.
Gene: Protein-coding gene on chromosome 6 (144,285,335 to 144,853,034, forward strand). Ensembl gene ENSG00000152818.
Subcellular location: Postsynaptic cell membrane; Cytoplasm, cytoskeleton
Subcellular location (Human Protein Atlas): Plasma membrane; Basal body; Nucleoplasm; Primary cilium
Pathways (Reactome):
Developmental Biology: EGR2 and SOX10-mediated initiation of Schwann cell myelination
Extracellular matrix organization: Formation of the dystrophin-glycoprotein complex (DGC)
Gene Ontology:
Molecular function: actin binding; integrin binding; protein binding; protein kinase binding; vinculin binding; protein-containing complex binding; zinc ion binding
Biological process: positive regulation of cell-matrix adhesion; muscle contraction; muscle organ development; regulation of sodium ion transmembrane transport; synaptic signaling
Cellular component: contractile ring; cytoplasm; extracellular exosome; filopodium; filopodium membrane; plasma membrane; protein-containing complex; cytoskeleton; cytosol; dystrophin-associated glycoprotein complex; membrane; neuromuscular junction; postsynaptic membrane; sarcolemma; synapse
Genetic constraint (gnomAD): Loss-of-function variants: 269 observed, 447.44 expected, observed/expected ratio (o/e) 0.6, 90% interval 0.54 to 0.67. The upper end of that interval is the gene's LOEUF score, 0.67, which puts it in group 2 of 6, group 1 being the genes least tolerant of losing a copy. Missense variants: 3,833 observed, 4,117.5 expected, observed/expected ratio (o/e) 0.93, 90% interval 0.91 to 0.96. Synonymous variants: 1,408 observed, 1,455.5 expected, observed/expected ratio (o/e) 0.97, 90% interval 0.93 to 1.01.
Homologues: Orthologues: chimpanzee UTRN (99% identical), macaque UTRN (97% identical), pig UTRN (92% identical), rabbit UTRN (92% identical), guinea pig UTRN (89% identical), mouse Utrn (88% identical), rat Utrn (86% identical), tropical clawed frog utrn (68% identical), zebrafish utrn (37% identical). Paralogues in human: DMD (50% identical), MACF1 (17% identical), DST (17% identical), PLEC (15% identical), SYNE1 (14% identical), DRP2 (14% identical), SYNE2 (13% identical), SPTB (12% identical), SPTBN1 (12% identical), SPTBN2 (12% identical), SPTBN4 (12% identical), SPTBN5 (11% identical), and 24 more.
Diseases named in the same sentence as UTRN in open-access papers:
UTRN is named in the same sentence as 52 diseases in open-access papers, as found by Europe PMC text mining. Sharing a sentence is not in itself a finding about the gene and the disease. The quoted sentences say what the papers report.
Duchenne muscular dystrophy (50 papers, 2011 to 2026). Duchenne muscular dystrophy (DMD) is a neuromuscular disease characterized by rapidly progressive muscle weakness and wasting due to degeneration of skeletal, smooth and cardiac muscle. "In the murine model of the Duchenne muscular dystrophy (the dystrophin/utrophin-deficient mouse) large clusters of nestin+ striated cells co-expressing cardiac troponin I, desmin and connexin 43, were present in the hearts near the end stage of the disease." (PMID 36690826, 2024). "For example, utrophin is well known to compensate for the loss of dystrophin in mice and results in a much milder phenotype than in human Duchenne muscular dystrophy." (PMID 26693275, 2015). "Furthermore, pharmacological enhancement of utrophin expression, a gene exclusively expressed in fetus but that can compensate Dystrophin loss of function in Duchenne Muscular Dystrophy is currently under investigation." (PMID 27805016, 2016). "Decreased levels of α-DGN have been reported in the serum of patients with Duchenne muscular dystrophy (DMD) and in the serum of utrophin-deficient mdx mice, a mouse model for DMD." (PMID 36723429, 2023). "In contrast, decreased levels of α-DGN have been reported in the serum of patients with Duchenne muscular dystrophy (DMD) and in the serum of utrophin-deficient mdx mice, a mouse model for DMD." (PMID 31097590, 2019). "The utrophin-dystrophin deficient (DKO) mouse model has been widely used to understand the progression of Duchenne muscular dystrophy (DMD)." (PMID 25859846, 2015). "Utrophin is a dystrophin homologue currently under investigation as a protein replacement therapy for Duchenne muscular dystrophy." (PMID 36587764, 2023). "We conclude that epigenetic manipulation of utrophin expression is a promising approach for the treatment of Duchenne Muscular Dystrophy (DMD)." (PMID 35859073, 2022). "In a utrophin-dystrophin DKO mouse model of Duchenne muscular dystrophy (DMD), we found upregulation of SLN expression in extensor digitorum longus (EDL), quadriceps, and diaphragm." (PMID 33732165, 2021). "Upregulation of utrophin, a dystrophin related protein, is considered a promising therapeutic approach for Duchenne muscular dystrophy (DMD)." (PMID 33298994, 2020). "Chemical proteomics and phenotypic profiling illustrate the aryl hydrocarbon receptor (AhR) is a target of ezutromid, the first‐in‐class utrophin modulator for the treatment of Duchenne muscular dystrophy." (PMID 31755636, 2020). "Up-regulation of utrophin in muscles represents a promising therapeutic strategy for the treatment of Duchenne Muscular Dystrophy." (PMID 32332749, 2020). "Following on from ezutromid, the first-in-class benzoxazole utrophin modulator that progressed to Phase 2 clinical trials for the treatment of Duchenne muscular dystrophy, a new chemotype was designed to optimise its physicochemical and ADME profile." (PMID 32713969, 2020). "Our results indicate that muscle biopsies from Becker muscular dystrophy patients have fewer numbers of regenerating fibres and reduced utrophin intensity compared to muscle biopsies from Duchenne muscular dystrophy patients." (PMID 26974331, 2016). "Utrophin upregulation could therefore be a therapeutic strategy in Duchenne Muscular Dystrophy (DMD) that arises from mutation in dystrophin gene." (PMID 26230628, 2015). "Western blotting was used to determine the levels of Pitx2 in whole tissue lysates from EOM and TA of mdx:utrophin+/− (Het) mice, a mouse model of Duchenne muscular dystrophy, compared to EOM and TA of wild-type mice." (PMID 23505501, 2013). "Utrophin is a protein homologous to dystrophin, the protein missing in Duchenne muscular dystrophy (DMD) patients." (PMID 24295286, 2013). "The functional replacement of utrophin for dystrophin is one of many attractive therapeutic strategies for the treatment of Duchenne muscular dystrophy." (PMID 23282144, 2013).
Duchenne muscular dystrophy (continued). "Therapeutic strategies to replace defective dystrophin with utrophin in patients with Duchenne muscular dystrophy require full-characterization of both these proteins to assess their degree of structural and functional equivalence." (PMID 22911693, 2012). "For instance, the small-leucine rich proteoglycan biglycan regulates the expression of utrophin in myotubes as well as in murine sarcolemma, and systemic delivery of recombinant human biglycan decreased fibrosis in a murine model (mdx model) of Duchenne muscular dystrophy." (PMID 37036009, 2023). "For example, the upregulation of utrophin via its 5′ UTR may be used for the treatment of Duchenne muscular dystrophy." (PMID 33575118, 2021). "For example, in Duchenne Muscular Dystrophy, studies using the mdx mouse model or the more severe mdx/utrophin double-knockout model have reported both exhaustion and depletion of satellite cells as result of continuous satellite cell activation during disease progression." (PMID 30404653, 2018). "L-arginine induces the expression of utrophin in skeletal muscle cells, so it has been proposed as a pharmacological treatment to attenuate the symptoms of Duchenne muscular dystrophy (DMD)." (PMID 40224962, 2025). "These homologous proteins are normally present at different subcellular domains; however, when DMD is defective (e.g., Duchenne muscular dystrophy), UTRN is upregulated and can compensate for its function." (PMID 33101375, 2020). "SMT C1100 is a utrophin modulator being evaluated as a treatment for Duchenne muscular dystrophy (DMD)." (PMID 27055247, 2016). "In Duchenne muscular dystrophy (DMD), utrophin, an autolog of dystrophin, can to some extent substitute for the missing dystrophin." (PMID 21970816, 2011). "Utrophin is the autosomal homolog of dystrophin, the product of the Duchenne Muscular Dystrophy (DMD) locus." (PMID 22216264, 2011). "Łoboda, Chamberlain, and Dulak review genetic strategies for Duchenne muscular dystrophy, focusing on exon skipping, gene replacement, and CRISPR-Cas9 editing to restore dystrophin or upregulate utrophin." (PMID 41328300, 2025). "Moreover, they showed that transcriptional induction of utrophin, a protein product which is very similar to dystrophin, improved muscle strength in a mouse model of Duchenne muscular dystrophy (DMD) by local application of the AAV-gRNAs." (PMID 35097003, 2021). "Dystrophin/utrophin double-knockout (dKO) mice develop a more severe and progressive muscular dystrophy than the mdx mice, the most common murine model of Duchenne muscular dystrophy (DMD)." (PMID 29078808, 2017). "Duchenne Muscular Dystrophy is characterized by: near absence of dystrophin in skeletal muscles; low percentage of revertant myofibers; up-regulation of utrophin synthesis; and a high degree of muscle fibrosis." (PMID 26015394, 2015). "In Duchenne muscular dystrophy, where dystrophin is lacking, utrophin is strikingly upregulated." (PMID 30764835, 2019). "For instance, in Duchenne Muscular Dystrophy (DMD), absence of dystrophin at the sarcolemma is compensated to some extent by utrophin during early gestational stages." (PMID 31710288, 2019).
muscular dystrophy (29 papers, 2007 to 2025). Muscular dystrophy (MD) refers to a group of more than 30 genetic diseases characterized by progressive weakness and degeneration of the skeletal muscles that control movement. "Compared to archived control muscle, immunofluorescent staining was absent for the rod- and carboxy-terminus of dystrophin in all three cases, with upregulation of utrophin consistent with a diagnosis of a dystrophin-deficient muscular dystrophy." (PMID 37628610, 2023). "There is evidence from dystrophin-deficient mouse models that increasing levels of utrophin at the muscle fibre sarcolemma by genetic or pharmacological means significantly reduces the muscular dystrophy pathology." (PMID 26974331, 2016). "In chimaeric mice deficient in DG rescued from the embryonic lethality, skeletal muscle differentiated normally but they developed a progressive muscular dystrophy reminiscent in many respects of that of mice with double mutations in dystrophin and utrophin." (PMID 26380289, 2015). "It is now well established that ectopic expression of utrophin prevents muscular dystrophy both in mdx mice and in utrophin-dystrophin deficient mice." (PMID 17712422, 2007). "Mouse studies suggested that utrophin may serve as a functional substitute for the dystrophin gene and can be viewed as a rescue protein in muscular dystrophy caused by abnormal dystrophin expression." (PMID 20950417, 2010). "Although it remains unknown whether dystroglycan interacts with specific dystrophins or utrophin paralogues during fetal brain development, genetic loss of dystroglycan recapitulates the brain abnormalities observed in these congenital muscular dystrophies called dystroglycanopathies." (PMID 34546327, 2021). "Alternatively, the codon‐optimized miniaturized utrophin, which serves as the autologous homologue of dystrophin, has been reported to prevent the muscular dystrophy phenotype in mouse and dog models." (PMID 39949979, 2025). "In a more recent approach that overcomes the large size of dCas9 fused to a transcriptional activation domain, a dual-rAAV9 system was successfully used to elevate the utrophin levels and ameliorate muscular dystrophy in mdx mice." (PMID 37917377, 2024). "Utrophin is also upregulated and localized along the sarcolemma in regenerating fibers of patients with muscular dystrophy, and transgenic overexpression of utrophin suppresses the dystrophic phenotype of mdx mice." (PMID 35939054, 2022). "We chose the EDL muscle because it is most frequently characterized in ex vivo physiological studies on muscular dystrophy while the soleus was chosen because utrophin expression is >3-fold higher in mouse soleus than in EDL24." (PMID 30914715, 2019). "Evidence of utrophin-independent reduction in muscular dystrophy pathology was demonstrated recently by crossing a transgenic PGC-1α mouse to the severely affected dystrophin/utrophin double knockout mouse." (PMID 27430020, 2016). "James Ervasti and colleagues show that injection of a truncated form of utrophin transduced all tissues examined, integrated with members of the dystrophin complex, and reduced serum levels of creatine kinase in a mouse model of muscular dystrophy." (PMID 19478831, 2009). "Importantly, skeletal muscle-specific PGC1α transgene expression was able to ameliorate muscle damage also in mice lacking both dystrophin and utrophin, indicating that PGC1α can protect against muscular dystrophy independently of utrophin." (PMID 39717824, 2024). "Furthermore, in the context of muscular dystrophies, the zebrafish model lacks the utrophin gene, which plays a compensatory role in humans." (PMID 39791729, 2024). "Therefore, there is evidence for both utrophin-dependent and oxidative fiber-dependent improvement in muscular dystrophy phenotypes." (PMID 27430020, 2016). "We postulated that P-188 NF might protect diaphragm muscle membranes from contraction-induced injury in mdx and mdx/utrophin-/- (dko) muscular dystrophy models." (PMID 26248188, 2015).
muscular dystrophy (continued). "Several agents upregulate utrophin (UTRN), a gene that we find downregulated in PDX5 versus PDX1 in our analysis, and are currently being tested for their use in the treatment of muscular dystrophy." (PMID 36675105, 2023). "Studies originally performed in a mouse model of DMD demonstrated enormous potential of both the full-length and truncated utrophin in compensating for the lack of dystrophin and preventing muscular dystrophy." (PMID 37917377, 2024). "Mdx/Galg2 transgenic mice displayed no signs of muscular dystrophy attributed to increased utrophin and other UGC components at the sarcolemma." (PMID 37917377, 2024). "Consequently in some muscular dystrophies, including DMD and BMD, utrophin is present at the muscle fibre sarcolemma due to the significant regeneration taking place, in addition to the up-regulation in DMD and BMD that is present in the absence of dystrophin." (PMID 26974331, 2016). "Our observations that SIRT1 transgenic muscle consists of higher percentage of slow-twitch oxidative myofibers and express high levels of utrophin and NMJ genes prompted us to test whether SIRT1 overexpression protects from muscular dystrophy." (PMID 25032964, 2014). "Although the difference in the amount of utrophin obtained in our experiment was not statistically significant between both treatment groups, we cannot completely rule out the potential role of utrophin as a mediator of the improvements against muscular dystrophy." (PMID 34377959, 2021). "However, the overexpression of DG in transgenic mice onto an mdx background did not inhibit muscular dystrophy; on the contrary, it exacerbated the phenotype by decreasing the utrophin and sarcoglycans expression at the sarcolemma." (PMID 26380289, 2015).
dystrophin deficiency (11 papers, 2009 to 2023). "Dystrophin deficiency can be compensated by upregulation of utrophin, an autosomal homologue of dystrophin." (PMID 31998814, 2019). "Utrophin is homologous with dystrophin and upregulated in dystrophin deficiency, potentially serving as a dystrophin surrogate." (PMID 28028563, 2017). "Our results highlight the effectiveness of utrophin in alleviating mitochondrial pathology resulting from dystrophin deficiency." (PMID 29065908, 2017). "The beneficial effects of combining such therapies should theoretically be additive with the prediction that the cumulative increase in utrophin levels would be sufficient to substantially prevent or delay the phenotypes associated with dystrophin deficiency." (PMID 19478831, 2009). "The overexpression of plectin in mdx muscle could be seen as a cellular response to dystrophin deficiency that counteracts the compensatory action of upregulated utrophin under these conditions." (PMID 23758845, 2013). "We conclude that the enhanced protein transduction gained by reducing the molecular weight of utrophin overcomes any loss of TAT-μUtr's biological function and propose TAT-μUtr as a potential direct protein replacement therapy for dystrophinopathies." (PMID 19478831, 2009). "Taken together, our data suggest that the mechanical properties of utrophin may be tuned by phosphorylation, with the potential to improve its efficacy as a protein replacement therapy for dystrophinopathies." (PMID 36587764, 2023). "Upregulated expression of utrophin has been found in dystrophinopathies and other disorders of muscle, including congenital myopathies, inflammatory myopathies, diabetic neuropathies, amyotrophic lateral sclerosis, spinal muscular atrophies, and minimal change myopathies." (PMID 32918390, 2020). "Similarly to dystrophin, overexpression of utrophin can improve the membrane stability of dystrophic myofibers and suppress the functional signs of dystrophinopathy." (PMID 30304405, 2019). "Therefore, we sought to determine whether TAT-mediated full-length or micro-utrophin delivery is a viable therapeutic option for the treatment of dystrophinopathy." (PMID 19478831, 2009). "The generation of transgenic mdx mice established that ubiquitous over-expression of full-length utrophin, and its continuous localization along the muscle membrane suppresses histophysiological signs of dystrophinopathy in a dose dependent manner with no detrimental effect." (PMID 30304405, 2019).